ENSG00000238764
Synonyms: LOC124905270
Gene: Small nucleolar RNA gene on chromosome X (17,357,930 to 17,358,033, forward strand). Ensembl gene ENSG00000238764.
Gene Ontology:
Biological process: RNA processing
Cellular component: nucleolus
Homologues: Paralogues in human: SNORD13D (82% identical), SNORD13E (82% identical), SNORD13P3 (82% identical), SNORD13 (81% identical), SNORD13P1 (78% identical).